RPL13P5 (ribosomal protein L13 pseudogene 5)
Synonyms: RPL13-2; RPL13L; RPL13_4_1199; RRPL13L
Gene: Transcribed processed pseudogene on chromosome 12 (6,883,996 to 6,884,613, forward strand). Ensembl gene ENSG00000240370.
Diseases named in the same sentence as RPL13P5 in open-access papers:
RPL13P5 is named in the same sentence as 2 diseases in open-access papers, as found by Europe PMC text mining. Sharing a sentence is not in itself a finding about the gene and the disease. The quoted sentences say what the papers report.
Alzheimer disease (1 paper, 2012). A progressive, neurodegenerative disease characterized by loss of function and death of nerve cells in several areas of the brain leading to loss of cognitive function such as memory and language. "LOC283345, known as RPL13P5, is ranked by all three feature selection methods as one of the best 20 genes, although we have not found any link to Alzheimer’s disease." (PMID 23066814, 2012).
RPL13P5 also shares sentences with these, for which no sentence is quoted: Sepsis (1 paper).